PPP2R2B (protein phosphatase 2 regulatory subunit Bbeta)
Diseases named in the same sentence as PPP2R2B in open-access papers (continued):
Sharing a sentence is not in itself a finding about the gene and the disease.
PPP2R2B also shares sentences with these, for which no sentence is quoted: Ataxia (7 papers); myotonic dystrophy type 1 (6); amyotrophic lateral sclerosis (3); ductal carcinoma in situ (3); Huntington disease (3); schizophrenia (3); Tremor (3); Astrocytoma (2); breast tumors (2); essential tremor (2); fragile X-associated tremor/ataxia syndrome (2); Gait ataxia (2); genetic disease (2); Huntington disease-like 2 (2); invasive breast carcinoma (2); acquired ataxia (1); Action tremor (1); acute lymphoblastic leukemia (1); Anxiety (1); autosomal dominant cerebellar ataxia (1); autosomal dominant disease (1); Boucher–Neuhauser Syndrome (1); brain disorder (1); cerebellar degeneration (1); cerebrovascular disease (1); COVID-19 (1); developmental delay (1); dysautonomia (1); Friedreich ataxia (1); frontotemporal dementia (1).
A further 28 diseases each share a sentence with PPP2R2B in 1 paper.